ATP6V1B1 (ATPase H+ transporting V1 subunit B1)
Diseases named in the same sentence as ATP6V1B1 in open-access papers:
ATP6V1B1 is named in the same sentence as 43 diseases in open-access papers, as found by Europe PMC text mining. Sharing a sentence is not in itself a finding about the gene and the disease. The quoted sentences say what the papers report.
distal renal tubular acidosis (16 papers, 2012 to 2026). A kidney disorder of impaired net acid secretion by the distal tubule characterized by hyperchloremic metabolic acidosis. "According to the Online Mendelian Inheritance in Man (OMIM) database, ATP6V1B1 associates with distal renal tubular acidosis 2 with progressive sensorineural hearing loss (MIM 267300) as syndromic phenotype." (PMID 34609590, 2022). "Distal renal tubular acidosis with HI was found to be associated with variants in ATP6V1B1 gene with a total of 85 reported mutant alleles (n = 85/269; 31.6%)." (PMID 34609590, 2022). "Studies from Africa reported ATP6V1B1 association with distal renal tubular acidosis patients with sensorineural HI." (PMID 34609590, 2022). "ATP6V0A4 was identified as an early causative gene of distal renal tubular acidosis (dRTA) along with the gene encoding subunit B1, ATP6V1B1." (PMID 37465367, 2023). "Hereditary distal renal tubular acidosis (dRTA) is a rare disease of H+ excretion defect of α-intercalated cells in renal collecting duct, caused by decreased V-ATPase function due to mutations in the ATP6V1B1 or ATP6V0A4 genes." (PMID 32123165, 2020). "ATP6V1B1 and ATP6V0A4 are the major pathogenic genes related to distal renal tubular acidosis (dRTA), a hereditary disease distinguished by metabolic acidosis, severe hyperchloremia, impaired bone growth and SNHL." (PMID 30686976, 2018). "Moreover, it was reported that primary distal renal tubular acidosis was a genetic disease caused by the mutation in ATP6V0A4 and ATP6V1B1, which can encode transporters that regulate acid-base balance in collecting tubes." (PMID 36408280, 2022). "Pathogenic variants in the B1 and a4 subunits of H+-ATPase (ATP6V1B1, ATP6V0A4) and in AE1 (SLC4A1) have been identified as the cause of distal renal tubular acidosis (dRTA) almost two decades ago." (PMID 38448728, 2024). "Hereditary distal renal tubular acidosis (dRTA) is caused by mutations of genes encoding subunits of the H+-ATPase (ATP6V0A4 and ATP6V1B1) expressed in α-intercalated cells of the distal renal tubule and in the cochlea." (PMID 22966473, 2012).
sensorineural hearing loss (7 papers, 2009 to 2026). "Among the genetic causes of autosomal recessive dRTA, mutations in the ATP6V1B1 gene are particularly important due to their association with early-onset disease and sensorineural hearing loss." (PMID 41897147, 2026). "Cases bearing ATP6V1B1 mutations usually accompany with early sensorineural hearing loss (SNHL), while ones caused by ATP6V0A4 mutations commonly comorbid with late-onset SNHL or normal hearing." (PMID 30558562, 2018). "The recessive form of the disease (which is usually associated with sensorineural deafness) is attributable to mutations in ATP6V1B1 or ATP6V0A4, which encode the tissue-restricted B1 and a4 subunits of the renal apical H+-ATPase." (PMID 26068435, 2015). "The importance of these specialized functions is underscored by the fact that mutations in the gene encoding the B1 subunit, Atp6v1b1, are associated with childhood sensorineural hearing loss and dRTA." (PMID 19214237, 2009). "We aim to identify molecular defects present in the ATP6V1B1, ATP6V0A4 and SLC4A1 genes in a Tunisian cohort, according to the following algorithm: first, ATP6V1B1 gene analysis in dRTA patients with sensorineural hearing loss (SNHL) or unknown hearing status." (PMID 24252324, 2013). "For example, RTA had been reported to be related to the SLC4A1, ATP6V1B1 and ATP6V0A4 genes, and mutations in ATP6V1B1 and ATP6V0A4 genes were predisposed to causing sensorineural hearing loss in children." (PMID 41311422, 2025). "In comparison, ATP6V1B1 and ATP6V0A4 genes have only AR genetic pattern, which is more likely to be combined with sensorineural hearing loss (SNHL)." (PMID 35612621, 2022).
hearing loss (6 papers, 2013 to 2025). "First, although knockout mice can recapitulate sensorineural hearing loss found in patients with ATP6V1B1 or ATP6V0A4 mutations, exactly how V-ATPase functions in hearing is not fully understood." (PMID 34296747, 2021). "Some patients with distal renal tubular acidosis that have mutations in ATP6V1B1 or ATP6V0A4, which encode the V-ATPase V1B1 and Voa4 subunits, respectively, develop sensorineural hearing loss, which is typically caused by damage to the sensory hair cells and/or nerve fibers of the inner ear." (PMID 34296747, 2021).
deafness (4 papers, 2009 to 2022). An inherited or acquired condition characterized by the complete loss of the ability to hear from one or both ears. "In 1999, renal tubular acidosis with deafness was the first phenotype linked to the V-ATPase with mutations in the kidney-specific isoforms ATP6V1B1 (MIM 267300) or ATP6V0A4 (MIM 602722) (refs 3, 4, 5)." (PMID 27231034, 2016). "Additionally, there are genetic variants associated with deafness or late-onset deafness (e.g., ATP6V1B1 and ATP6V0A4)." (PMID 35346296, 2022). "These include deafness as reported in family 1, and also reported for ATP6V0A4 and ATP6V1B1 defects." (PMID 27231034, 2016).
ovarian carcinoma (4 papers, 2021 to 2025). A malignant neoplasm originating from the surface ovarian epithelium. "Gain- and loss-of-function experiments demonstrated that ATP6V1B1 promotes the proliferation, migration, and invasion of ovarian cancer cells in vitro, while ATP6V1B1 knockout inhibits tumor growth in vivo." (PMID 38735913, 2025). "Analysis of the GEPIA database revealed that ATP6V1B1 expression was significantly increased in ovarian cancer tissue, and Kaplan‒Meier plotter revealed that ATP6V1B1 expression was associated with poor progression-free survival." (PMID 38735913, 2025). "Similarly, in ovarian cancer, ATP6V1B1 has been implicated in modulating tumor progression and chemotherapy resistance through the mTOR/autophagy pathway." (PMID 40463372, 2025). "Compared with cisplatin treatment alone, ATP6V1B1 inhibition and cisplatin treatment synergistically increased the percentage of apoptotic ovarian cancer cells." (PMID 38735913, 2025). "We further compared ATP6V1B1 expression in normal ovarian cells (IOSE80) with that in ovarian cancer cell lines (A2780, SKOV3, CAOV3)." (PMID 38735913, 2025). "We observed the overexpression of ATP6V1B1 in ovarian cancer tissues and cells, and silencing ATP6V1B1 suppressed the proliferation, migration, and invasion abilities of ovarian cancer cells, while increasing the sensitivity of cells to cisplatin." (PMID 38735913, 2025). "Our data show that ATP6V1B1 is upregulated in ovarian cancer and correlated with decreased progression-free survival." (PMID 38735913, 2025). "To investigate the role of ATP6V1B1 in ovarian cancer, we downregulated and upregulated ATP6V1B1 expression in SKOV3 and A2780 cells, respectively." (PMID 38735913, 2025). "In summary, our study indicated that ATP6V1B1 is an oncogene involved in the pathogenesis of ovarian cancer." (PMID 38735913, 2025). "This study revealed that ATP6V1B1 is an oncogenic factor that is highly expressed in ovarian cancer tissues and cell lines." (PMID 38735913, 2025). "Our findings indicate that ATP6V1B1 knockdown increases the cisplatin sensitivity of ovarian cancer cells." (PMID 38735913, 2025). "This study aimed to investigate the molecular mechanism of ATPase H+-Transporting V1 Subunit B1 (ATP6V1B1) in ovarian cancer development and chemoresistance." (PMID 38735913, 2025). "To assess the role of ATP6V1B1 in ovarian cancer progression in vivo, we established a nude mouse tumor xenograft model using the SKOV3 cell line." (PMID 38735913, 2025). "Overall, our study confirmed the oncogenic role of ATP6V1B1 in ovarian cancer and revealed that ATP6V1B1 promotes ovarian cancer progression via the mTOR/autophagy axis." (PMID 38735913, 2025). "We also showed that reduced ATP6V1B1 expression inhibited the proliferation, migration and invasion of ovarian cancer cells." (PMID 38735913, 2025). "A recent study has revealed that ATP6V1B1 is overexpressed in ovarian cancer tissues and platinum-resistant ovarian tissues." (PMID 38735913, 2025). "We observed overexpression of ATP6V1B1 in ovarian cancer tissues and three distinct ovarian cancer cell lines." (PMID 38735913, 2025). "The involvement of ATP6V1B1 in regulating the cell cycle of ovarian cancer has been established." (PMID 38735913, 2025). "The invasion of ovarian cancer cells was enhanced by the overexpression of ATP6V1B1." (PMID 38735913, 2025). "In summary, ATP6V1B1 can promote the proliferation of ovarian cancer cells." (PMID 38735913, 2025). "In our research, we investigated whether ATP6V1B1 affects the migration and invasion of ovarian cancer cells." (PMID 38735913, 2025). "In summary, our study further confirmed the oncogenic role of ATP6V1B1 in ovarian cancer." (PMID 38735913, 2025). "Ovarian cancer cells may promote cellular migration and invasion by upregulating ATP6V1B1 to enhance MMP activity or interaction with actin, but further mechanistic studies will be needed." (PMID 38735913, 2025).
ovarian carcinoma (continued). "In this study, we investigated the role of ATP6V1B1 in the pathogenesis of ovarian cancer." (PMID 38735913, 2025). "Our study revealed that ATP6V1B1 may play an important role in the process of macroautophagy in ovarian cancer cells, but more specific interaction experiments are needed to demonstrate the role of ATP6V1B1 in this process." (PMID 38735913, 2025). "In addition, knocking down ATP6V1B1 increases the sensitivity of ovarian cancer cells to cisplatin." (PMID 38735913, 2025). "The objective of this study was to investigate the potential role of ATP6V1B1 in the progression of ovarian cancer and its ability to regulate the mechanism of ovarian cancer cell death, to identify insights and therapeutic targets for the diagnosis and treatment of ovarian cancer." (PMID 38735913, 2025). "ATP6V1B1 levels were markedly elevated in ovarian cancer (OC) samples compared with nontumor." (PMID 38735913, 2025).
nephrocalcinosis (3 papers, 2019 to 2025). Nephrocalcinosis is a disorder that occurs when too much calcium is deposited in the kidneys. "The additional ablation of the B1 subunit of the H+-ATPase resulted in nephrocalcinosis, renal insufficiency, bone loss and poor growth in Trpv5 Atp6v1b1 dKO mouse model." (PMID 38339056, 2024). "It is important to mention the difference in nephrocalcinosis between Atp6v1b1 KO mice and patients with ATP6V1B1 mutations." (PMID 38339056, 2024). "Importantly, mice with a disruption on Atp6v1b1, the ortholog of which in humans causes dRTA, also lack the hypercalciuria, nephrocalcinosis and overt acidemia seen in these patients, pointing to some limitations inherent to these mouse models." (PMID 40289527, 2025). "The difference in phenotype between Trpv5 Atp6v1b1 dKO and Cldn16 Atp6v1b1 dKO extends beyond nephrocalcinosis." (PMID 38339056, 2024). "Urine alkalinization, caused by the deletion of Atp6v1b1, was shown to be important in inducing nephrocalcinosis in hypercalciuric mice lacking transient receptor potential vanilloid 5 (TRPV5)." (PMID 38339056, 2024). "Human patients with mutations in ATP6V1B1 develop distal renal tubule acidosis (dRTA) and suffer from nephrocalcinosis, while mice with Atp6v1b1 deletion show urine alkalinization with no systemic acidosis or nephrocalcinosis." (PMID 38339056, 2024). "Von Kossa staining and Alizarin Red S staining showed the absence of nephrocalcinosis in Cldn16 KO male and in Cldn16 Atp6v1b1 dKO counterpart mice." (PMID 38339056, 2024). "This conclusion is based on the absence of nephrocalcinosis despite the urine alkalinization induced by the additional deletion of the Atp6v1b1 gene in the Cldn16 Atp6v1b1 dKO model." (PMID 38339056, 2024). "The injury caused by nephrocalcinosis cannot explain the complex phenotype of Trpv5 Atp6v1b1 dKOs, especially since other mouse models with nephrocalcinosis (Cldn2 KO and Cldn10 ksp cKO) do not develop this severe pathology." (PMID 38339056, 2024). "In contrast to Trpv5 Atp6v1b1 dKO, in our Cldn16 Atp6v1b1 dKO the alkalinization in the urine did not lead to nephrocalcinosis." (PMID 38339056, 2024). "By showing that urine alkalinization does not induce nephrocalcinosis in hypercalciuric mice lacking claudin-16 due to the deletion of Atp6v1b1, we emphasize the multifactorial nature of this pathology." (PMID 38339056, 2024).
renal tubular acidosis (3 papers, 2016 to 2024). A group of genetic disorders of the kidney tubules characterized by the accumulation of metabolically produced acids with elevated plasma chloride, hyperchloremic metabolic acidosis. "One example of such an ionocyte-related disease is that caused by mutations in ATP6V1B1, in which patients present with severe renal tubular acidosis often accompanied by hearing loss." (PMID 36864051, 2023).
hydronephrosis (2 papers, 2016 to 2024). Collection of urine in the renal pelvis that results in dilatation of the renal pelvis and calyces. "Trpv5 Atp6v1b1 dKO mice showed retarded growth directly after birth, 80% of these mice died within 6 weeks after birth and bilateral hydronephrosis in addition to abnormal dilation of the collecting ducts was observed." (PMID 38339056, 2024).
nephrolithiasis (2 papers, 2019 to 2022). The presence of a calculus in the pelvis of the kidney; this is most often composed of mineral salts and proteins. "Finally, the fly orthologs of two genes associated with nephrolithiasis, ATPase H+ Transporting V1 Subunit B1 (ATP6V1B1) and ATP6V0A4 (Vacuolar H+-ATPase 55kD subunit [Vha55] and Vha100-2 in flies), are highly expressed in Malpighian tubule principal cells." (PMID 35696569, 2022).
bladder cancer (1 paper, 2023). "Compared with normal bladder samples, the protein expression of PLOD1, ATP6V1B1, HSD17B1, SERPINB7, and PYCR1 in bladder cancer tissues was upregulated, while EGR1 in cancer tissues was down-regulated." (PMID 37880682, 2023).
calcium oxalate kidney stone (1 paper, 2022). "Mutations in ATP6V1B1 and ATP6V0A4 have been identified in calcium oxalate kidney stone patients, suggesting that they are essential for calcium oxalate kidney stone formation." (PMID 35696569, 2022).
HIV-1 infection (1 paper, 2025). The type species of lentivirus and the etiologic agent of acquired immunodeficiency syndrome (AIDS). "FNBP1L, ARHGAP24, and ATP6V1B1 knockdown repeatedly proved to increase HIV-1 infection in additional donors, confirming screening observations." (PMID 40029073, 2025). "Over a 7-day period in THP1 cells, knockdown of FNBP1L, ARHGAP24, and ATP6V1B1 resulted in sustained enhancement of HIV-1 infection." (PMID 40029073, 2025). "From this group, the actin cytoskeleton regulators FNBP1L and ARHGAP24, along with the vacuolar proton pump ATP6V1B1, were prioritized for further study due to their strong impact and lack of prior association with HIV-1 infection in the literature." (PMID 40029073, 2025). "Depletion of FNBP1L, ARHGAP24, and ATP6V1B1 showed increased entry rates upon HIV-1 infection." (PMID 40029073, 2025). "Knocking down FNBP1L, ARHGAP24, and ATP6V1B1 in CD4+ T cells did not enhance HIV-1 infection, contrasting sharply with the significant effects observed in MDDCs." (PMID 40029073, 2025). "In a selective, shRNA-mediated knockdown screen in primary monocyte-derived dendritic cells (MDDCs) infected with HIV in the presence of SAMHD1-disactivating Vpx containing virus-like particles, three proteins hampering HIV-1 infection were identified: FNBP1L, ARHGAP24, and ATP6V1B1." (PMID 40029073, 2025). "Our results show that the depletion of FNBP1L, ARHGAP24, and ATP6V1B1 enhances HIV-1 infection in MDDCs, but not in CD4+ T cells." (PMID 40029073, 2025).
inflammatory bone diseases (1 paper, 2025). "In addition, SCSP modulates inflammatory cascades by attenuating IL-17 signaling, Toll-like receptor pathways, and key genes implicated in inflammatory bone diseases, such as Ccl2, Il17re, Fosl1, Mmp13, Ccl5, Tlr1, Il12b, and Atp6v1b1." (PMID 40926992, 2025).
Kabuki syndrome (1 paper, 2022). Kabuki syndrome (KS) is a multiple congenital anomaly syndrome characterized by typical facial features, skeletal anomalies, mild to moderate intellectual disability and postnatal growth deficiency. "AD and AR were the most common pattern of inheritance, and the most frequent variant genes were SLC4A1 and KMT2D, which can, respectively, lead to the two most frequent diseases: dRTA (with inclusion of SLC4A1, ATP6V1B1, and ATP6VOA4 genes) and Kabuki syndrome." (PMID 35612621, 2022).
cancer (6 papers, 2007 to 2025). A tumor composed of atypical neoplastic, often pleomorphic cells that invade other tissues. "Subsequently, we explored the impact of ATP6V1B1 on cancer cell growth and proliferation using these cell lines." (PMID 38735913, 2025). "Additionally, decreasing ATP6V1B1 levels substantially reduced cancer cell invasion through the Matrigel extracellular matrix in both cell lines." (PMID 38735913, 2025). "Among the set of genes that we identify as being related to RCC, some were known from previous studies (e.g. ATP6V1B1, EGLN3, SLC25A5, TUBB, ALDOA); others had never before been associated with RCC, but have been identified with other cancers (e.g. ABL2, JAZF1, TFAP2A)." (PMID 19455236, 2007).
tumor (5 papers, 2007 to 2025). "Our results suggest that inhibition of ATP6V1B1 can induce lethal autophagy in tumor cells, thereby inhibiting cell growth." (PMID 38735913, 2025). "Although studies have shown that ATPases regulate autophagy, whether ATP6V1B1 regulates autophagy in tumor cells remains unknown." (PMID 38735913, 2025). "Notably, ATP6V1B1 expression was greater in OC tissues than in normal or benign tumor tissues." (PMID 38735913, 2025).
infection (2 papers, 2024 to 2025). The state of being infected such as from the introduction of a foreign agent such as serum, vaccine, antigenic substance or organism. "To illustrate the performance of the COCONUT normalization, we visualized the log2 expression values of commonly used house-keeping genes (ATP6V1B1, and GAPDH) and genes known to be modulated by infection (CEACAM1 and DYSF) as previously shown." (PMID 38817614, 2024). "While endocytosis still occurs without ATP6V1B1 (as shown by FITC-dextran uptake), the lack of acidification could allow endocytosed HIV-1 to escape degradation, enhancing infection." (PMID 40029073, 2025).
benign tumor (1 paper, 2025). "Here, we examined the expression of ATP6V1B1 mRNA and protein in normal ovarian tissues, benign tumor tissues and OC tissues by RT‒qPCR and immunohistochemistry (IHC)." (PMID 38735913, 2025).
ATP6V1B1 also shares sentences with these, for which no sentence is quoted: genetic disease (2 papers); Alport syndrome (1); Alstrom syndrome (1); biotinidase deficiency (1); Clouston syndrome (1); cystinuria (1); Dent disease (1); dentinogenesis imperfecta (1); erythrokeratodermia variabilis (1); Fanconi syndrome (1); Hearing impairment (1); Hypercalciuria (1); leprosy (1); lung adenocarcinoma (1); Marfan syndrome (1); nephropathies (1); ovarian tumors (1); primary hyperoxaluria (1); prostate carcinoma (1); Pseudoxanthoma elasticum (1); pyelonephritis (1); rheumatoid arthritis (1); serous ovarian cancer (1); Treacher-Collins syndrome (1); X-linked myopathy with excessive autophagy (1).